RN7SKP116 (RN7SK pseudogene 116)
Gene: Miscellaneous RNA gene on chromosome 6 (47,715,283 to 47,715,601, forward strand). Ensembl gene ENSG00000252711.
Homologues: Orthologues: chimpanzee 7SK (99% identical), mouse Gm55684 (37% identical). Paralogues in human: RN7SKP33 (58% identical), RN7SKP184 (58% identical), RN7SKP162 (58% identical), RN7SKP187 (56% identical), RN7SKP149 (56% identical), RN7SKP118 (56% identical), RN7SKP178 (55% identical), RN7SKP44 (55% identical), 7SK (55% identical), RN7SKP103 (55% identical), RN7SKP217 (55% identical), RN7SKP224 (55% identical), and 284 more.